IL2 (interleukin 2)
Diseases named in the same sentence as IL2 in open-access papers (continued):
Sharing a sentence is not in itself a finding about the gene and the disease.
tumor (continued). "Oestrogen decreased IFN-γ and IL-2 expression in T cells co-cultured with tumour cells, suggesting E2-induced inhibition of T cell function." (PMID 36581917, 2022). "TIL cultures are generated by first harvesting a tumor lesion, dissociating it into small fragments or a single cell suspension, culturing the cells in IL-2, and expanding them to therapeutic numbers." (PMID 35335089, 2022). "In conclusion, our management protocol of HB tumor rupture and peritoneal perfusion with IL-2 was an obligatory procedure to protect patients from peritonitis and peritoneal seeding." (PMID 35391745, 2022). "When comparing shMETTL3 and shMETTL3 + cisplatin to the control tumor, IL-2 was increased while IL-10 was decreased." (PMID 36429032, 2022). "LMP1 expressed by the EBV-infected cells promotes the proliferation of the tumor, which is further potentiated by the cytokine IL-2 secreted by immune cells in the TME." (PMID 35632758, 2022). "TILs are tumor-reactive T cells isolated from patients and then expanded ex vivo in the presence of interleukin (IL)-2 before reinfusion into the patients." (PMID 35845425, 2022). "We found that TNF-α, IFN-γ, and IL-2, which play vital roles in immunity against tumor growth, were relatively upregulated with these treatments (p< 0.05)." (PMID 35992834, 2022). "IL-2 preactivation clearly enhanced the NK-cell responsiveness of blood-derived NK-cells, whereas tumor-derived NK-cells still showed reduced cytolytic activity and diminished IFN-γ production." (PMID 35474089, 2022). "We find empirically and computationally that extending the tumor exposure of locally-injected interleukin-2 by increasing molecular size and/or improving matrix-targeting affinity improves therapeutic efficacy in mice." (PMID 35013154, 2022). "Inflammatory cells can change the tumor microenvironment through overproducing cytokines, including IL-2, IL-6, and TNF-α, thus promoting tumorigenesis and the proliferation, migration, and immune escape of tumor cells." (PMID 35872847, 2022). "An oncolytic vaccina virus expressing IL-2 enhanced the tumour infiltration of highly reactive tumour-specific endogenous CD8+ T cells in a mouse model of colon cancer, with a reduction of exhausted PD-1hiTim-3+CD8+ T cells and regulatory T cells." (PMID 35205725, 2022). "Their immunogenicity in boosting DC-driven anti-tumor immunity was greater than tumor lysate, and they increased splenocyte proliferation and IL-2 release in mouse leukemia and melanoma cancer models." (PMID 36612080, 2022). "The pre-clinical testing of targeted expression has mostly comprised IL-2-based NFAT promoters targeting IL-12 expression to the tumour site." (PMID 35205725, 2022). "Measuring both pro-inflammatory (e.g., IFNγ, TNFα, and IL-2) and anti-inflammatory cytokines (e.g., IL-4, IL-6, and IL-10) provides an indication of immune activity in the tumor." (PMID 35464481, 2022). "CT26 tumor-bearing BALB/c mice were injected intravenously with PBS as control or 50 ug of Alexa-647-Alb-IL2." (PMID 35962391, 2022). "Although various studies have assessed the effects of the IL-2 on the immune system leading to the evolvement of IL-2 application for tumor immunotherapy, several drawbacks hinder its utility." (PMID 36510217, 2022). "Treatment with Salmonella + Alb-IL2 resulted in significantly reduced tumor growth compared to Salmonella or Alb-IL2 treatment alone." (PMID 35962391, 2022). "Inactivation of CD4+ T cells will further cause a decrease in the secretion of IL-2 and IFN-γ, impairing cytotoxic T lymphocyte-mediated tumor killing activity." (PMID 35603146, 2022).
tumor (continued). "Another study with a super mutant IL-2 (sumIL-2) with decreased CD25 binding and increased CD122 (βIL-2R) binding, fused to a tumor-targeting antibody, revealed the therapeutic potential of antibody-cytokine fusion proteins comprising next-generation IL-2." (PMID 36569901, 2022). "Similar tumor reduction was observed when IL-2 was provided in a paracrine configuration, by co-injection of one cell type only expressing the anti-NY-ESO-1 TCR and a second cell type only expressing the synthetic IL-2 circuit." (PMID 36520915, 2022). "This suggests a direct connection between increase of IL-2 concentration in serum and the strength of tumor growth inhibition." (PMID 35954434, 2022). "Partially consistent with the Kaplan–Meier analysis, PGE2 and IL-6 were significant predictors of longer survival (P = 0.033 and 0.031, respectively), whereas IL-2 and IL-6 predicted tumor response to c4G12 treatment (P = 0.030 and 0.013, respectively)." (PMID 35665759, 2022). "Alternative ways for NK-cell activation and upregulation of NCRs comprise the stimulation of endogenous IL-2 production within the tumor microenvironment." (PMID 35474089, 2022). "Imprime’s establishment of this immuno-supportive microenvironment also allowed increased trafficking of activated cytotoxic T cells (CD8+/Ki67+/GrzB+) with effector phenotype (IFN-γ+/IL-2+/TNF-α+) into the tumor." (PMID 35692755, 2022). "Boletus lectins have been found to have mitogenic activity towards tumour cells, antimicrobial activity as well as inducing interleukin-1 and interleukin-2 cytokines." (PMID 35421104, 2022). "Based on our study, it is likely that tumor-infiltrating NK cells that reach hypoxic tumor sites in the presence of IL-2 upregulate HIF to enhance NK cell function." (PMID 34999917, 2022). "In the early 1980s, seminal studies by Rosenberg and colleagues showed that exposure of patient-derived peripheral blood mononuclear cells (PBMCs) to IL-2 alone generated cells that were able to recognize and kill tumor cells in vitro." (PMID 35720306, 2022). "Unfortunately, in clinical studies, the dosage of IL-2 administered to induce a significant tumor rejection led to severe toxicities, including vascular leak syndrome, heart failure, and liver toxicity in clinical trials." (PMID 36231109, 2022). "LAK cells obtained by 6-day cultivation with cytokine IL-2 released theTag7–Hsp70 cytotoxic complex into a conditioned medium after incubationwith target tumor cells." (PMID 33959389, 2021). "Extracellular Hsp70 either free or in exosomes together with other DAMPs derived from necrotic tumor cells can stimulate the release of pro-inflammatory cytokines including IL-2." (PMID 34079819, 2021). "TGF-β/IL-10 genes, known to play critical roles in inhibiting CD8 and CD4 T cell functions and IL-2/IFNγ genes, which are known to boost the anti-tumor immune response." (PMID 34728682, 2021). "IL-2 exerts its anti-tumor effect mainly by driving the proliferation and activation of NK cells and CD8+ TILs." (PMID 33746989, 2021). "Ranitidine alone, or in combination with IL-2, was also shown to reduce tumor progression in advanced malignant melanoma patients." (PMID 33931709, 2021). "IL-2 is the most commonly used cytokines for NK cell expansion, but IL-2 dose potentially promotes Treg expansion, which contributes to tumor tolerance." (PMID 33937033, 2021). "Compared to IL-2 conditioning, expanding T cells with IL-15 vastly improves mitochondrial fitness, prevents overt T cell differentiation and improves tumor immunity." (PMID 33815400, 2021). "These tandem CAR T cells had moderate increases in IFN-gamma and IL-2 secretion and improved tumor-killing capacity (~60% in tandem CAR vs~20% in biCAR in U373 model, p<0.05)." (PMID 34421912, 2021). "To explore if the non-IL2 blocking properties improve its efficacy, we sought to compare the efficacy of BT942 with daclizumab which blocks IL-2 signalling on IL-2R in the MC38 syngeneic tumor model in B-hIL2RA humanized mice." (PMID 34824364, 2021).
tumor (continued). "Tumor-bearing mice treated with T-cells and BiTEDs showed significantly elevated levels of systemic IL-2, IFN-γ, TNF-α, and IL-10, seven days after treatment." (PMID 33936101, 2021). "T cell clones were generated in the presence of 20 U/mL recombinant IL-2 and irradiated autologous tumor cells, PBLs, and EBV-transformed B cell lines." (PMID 34553029, 2021). "Here, we show that Ad5/3-E2F-d24-vIL2 is a promising candidate to overcome two main caveats that have restricted the clinical use of wt IL-2 cytokine therapy: low therapeutic levels in the tumor lesion, and severe systemic toxicity." (PMID 34084172, 2021). "Similar patterns were observed in TILs from B16.F10 tumors, where the bystander cells contained 1.5-fold more IFN-γ+ TNFα+, and 3.4-fold more IFN-γ+ IL-2+ cells compared to tumor-Ag sp." (PMID 34867942, 2021). "Systemic loss of miR-21 favored tumor progression with weakened CD4 and CD8 T cell antitumor responses characterized by impaired T cell proliferation and decreased IFN-γ and IL-2 secretion." (PMID 34830805, 2021). "In recent years, many studies have confirmed that the enhanced function of IL-2 can inhibit tumor occurrence and development." (PMID 34631520, 2021). "In TIL therapy, tumor biopsy is fragmented and plated in the presence of interleukine-2 (IL-2) for 2–4 weeks." (PMID 33522929, 2021). "Further phenotypic analysis revealed that in the presence of tumor-derived exosomes, it was the Treg population that responded to IL-2 in a TGF-β dependent manner." (PMID 34831378, 2021). "Initially TILs are isolated from homogenized tumor tissues or sentinel lymph nodes, then cultured with IL-2 in the presence of tumor lysate as an antigen source and gamma irradiated peripheral blood mononuclear cells (PBMCs) as feeder cells." (PMID 34484205, 2021). "Interferon-gamma (IFN-γ) and interleukin-2 (IL-2) expression in tumor tissue was much higher in mice treated with oxaliplatin with or without B. breve strains (B. bre JCM92 and B. bre Bb03) compared to IFN-γ and IL-2 expression in vehicle-treated mice." (PMID 33668827, 2021). "It has been demonstrated that this system prolonged IL-2 retention in the circulation in comparison to unmodified IL-2 free solution against EG7 tumor-bearing mice." (PMID 33668746, 2021). "In a murine tumor model, IL-2 secreted from tumor-resident CD4+ T cells increased CD8+ T cell proliferation and granzyme B expression." (PMID 34012451, 2021). "Our data indicate that EMT-high tumors lack CTL cytotoxic activity and hence tumor clearance due to limited support of IFNγ, TNFα, and IL2 and abundance of suppressive IL10 and TGFβ cytokines." (PMID 35096592, 2021). "Additional studies have shown increased tumor control in vivo with combinations of radiotherapy and IL-2 immunocytokines targeting CEA and EpCAM." (PMID 33803078, 2021). "IL-2 has been well established as a T cell growth factor and has been widely implemented to support strong anti-tumor T cell responses." (PMID 34804041, 2021). "Apart from suppressing T-cell proliferation and activation, experiments have shown that CD276 downregulates several cytokines, such as IFN-γ, TNF-a, and IL-2, while in vitro studies suggest its potential role in tumor invasion and metastasis as well." (PMID 33918733, 2021). "Human tumor-derived exosomes were shown to inhibit IL-2 mediated proliferation of CD4 and CD8 T cells." (PMID 34831378, 2021). "Third, in part due to this high affinity for the trimeric high-affinity receptor complex on immunosuppressive Tregs, a higher dose of IL-2 is necessary to achieve CTL-mediated immune killing of the tumor, which leads to severe toxicity in most patients." (PMID 33986267, 2021). "The first step in autologous TIL therapy was performed by TIL expansion using IL-2 from primary bladder tumors and then functionally selected by co-culture with autologous tumor and INF-γ measurement." (PMID 33802203, 2021).
tumor (continued). "TILT-123 was demonstrated active in transgene expression (TNFa and IL-2) and oncolytic potential in human and hamster tumor types." (PMID 33922052, 2021). "In the tumor samples, we detected the expression of IL-2 and TNF-α, which is associated with virus replication, confirming delivery of functional virus to the tumor." (PMID 32920593, 2021). "For example, IL-2 can potently activate both T-cells and nature killer cells, and is potentially applicable for tumor control." (PMID 34394124, 2021). "Treatment with DC vaccine leads to the secretion of tumor antigen-specific Th1 cytokine (IL-2 and IFN-γ) from the splenic lymphocytes." (PMID 34267616, 2021). "Selplg−/− T cells also had increased production of IFN-γ, TNF-α, and IL-2 which led to melanoma tumor control." (PMID 33708224, 2021). "In another experiment, i.v. treatment with ICO15K-cBiTE followed by three courses of T cell transfer plus IL-2 i.p. resulted in delayed tumor growth compared to groups receiving parental virus or PBS." (PMID 33863363, 2021). "We observed increased expression of the effector cytokines TNF-α and IL-2 concomitantly with decreased secretion of IL-10 in culture supernatants of tumor-infiltrating leukocytes treated ex vivo with activin-A." (PMID 34548096, 2021). "Similar results were seen in the context of targeting the tumor microenvironment with IL-2-based immunocytokines." (PMID 33803078, 2021). "The antibacterial and anti-tumor immune responses from the M1 macrophages are executed by releasing pro-inflammatory cytokines (such as IL-12, IL-1β, IL-2, IL-6, IL-23, and TNF-α), NO, ROS, and chemokines." (PMID 33883988, 2021). "When compared with controls, pCAR T cells demonstrated enhanced and more sustained IL-2 release over repetitive tumor re-stimulation, accompanied by increased gene expression related to JAK-STAT signaling." (PMID 35028604, 2021). "The generation of antitumor T cells is based on the extraction of TILs from surgically resected tumor fragments and ex vivo expansion with high doses of IL-2." (PMID 34066067, 2021). "Recent reports describe superior activity of BEMPEG over native IL‐2 in mouse models of adoptive T‐cell transfer and of tumor‐specific vaccination." (PMID 33152115, 2021). "In melanoma, IL-2-expressing MSCs were indicated to delay tumor growth, developing CD8-mediated tumor-specific anticancer immunity." (PMID 34736460, 2021). "Methods to study 3D NK infiltration into tumour spheroids have been proposed, through stimulation with different cytokines, such as IL-2 and IL-18." (PMID 34572836, 2021). "IFNα and IL-2 were the first cytokines to demonstrate antitumor effects in vivo; this observation led to the development of cytokines as anti-tumor monotherapies." (PMID 33968029, 2021). "The anti-tumor activity of allogenic and autologous memory-like NK cells is significantly greater than that displayed by NK cells stimulated overnight with IL-2." (PMID 34177887, 2021). "For example, ACT requires the isolation of T cells from the tumor, while IL-2 and the CPIs target T cells to mediate their effect." (PMID 34830973, 2021). "further proved that the simultaneous administration of interleukin (IL)-2 in vivo can enhance the anti-tumor efficacy." (PMID 34553029, 2021). "SLC3A2-specific CAR T cells demonstrated cytotoxicity against tumor cells, stimulated interferon-γ and interleukin-2 production in vitro." (PMID 34112739, 2021). "In high dose IL-2 therapy, efficacy is driven by the ability of IL-2 to enhance conventional and effector T and NK cell responses against tumor cells, but the therapeutic window is limited by significant and often severe toxicity." (PMID 33854514, 2021). "TILT-123 expresses two potent cytokines, tumor necrosis factor alpha and interleukin-2, to stimulate especially the T-cell compartment in the tumor microenvironment." (PMID 33513935, 2021).
tumor (continued). "IL-2 therapy introduced a new perspective on cancer treatment: instead of affecting cancer cells directly, it promotes anti-tumor responses through the stimulation of the host immune system." (PMID 34084172, 2021). "As a major assumption, the IL-2 stimulation ratio in blood was considered as a surrogate for target engagement in the tumor, and, thus, a potential marker for antitumor efficacy." (PMID 34371708, 2021). "Since systemic exposure to high-dose IL2 often results in grade 3 or 4 adverse events in patients, we tested the combination of T cells with a tumor-targeted IL2, as a strategy to reduce exposure to healthy organs and focus IL2 activity at the site of disease." (PMID 33796916, 2021). "CD4+ T cells have been shown to promote tumor regression via IL-2 secretion, by directly eliminating cancer cells or by augmenting tumor-specific CD8+ T cell function." (PMID 35087529, 2021). "The activation of the maternal immune system leads to an increase in the release of cytokines such as, IL-1β, IL-9, IL-17, Eotaxin-2 and IL2 in the tumor environment and subsequently in the maternal circulation." (PMID 34203890, 2021). "The treatment of NK cells with IL-15 helped to maintain anti-tumor activities in the context of an immunosuppressive microenvironment compared with IL-2 treated NK cells." (PMID 33732640, 2021). "Early work by several groups reported co-administration of mAb with the vasculature promoting agents: angiotensin II, tumor necrosis factor-alpha, interferon, and interleukin 2 led to between 40% and 200% increases in mAb tumor uptake." (PMID 35979855, 2021). "It was previously indicated that IL-2 expanded tumor-infiltrating lymphocytes (TILs) and has remarkable efficacy in immunogenic tumors 40, we herein tested combinatory effects of αPD-1 and IL-2 in our 3D-TSC system." (PMID 34646378, 2021). "We noticed relative reduction of IL-2 production by PD-1High T cells upon addition of co-cultured tumor cells in comparison with PD-1Low, and HuR-proficiency in 786–0 cells significantly imposed suppressive effects on IL-2 production." (PMID 33649535, 2021). "TH1 cytokines such as IFN-γ, TNF-α and IL-2 produced by TH1 cells contribute to inhibit tumor growth and activation of tumor-specific immune mechanisms." (PMID 34012451, 2021). "Neoadjuvant immunotherapy, including preoperative IL-2, has improved patient responses to surgery, likely due to improved tumor-specific CTL expansion." (PMID 33986267, 2021). "The biological mechanisms uncovered here support the continuation of ICI together with TNFa and IL-2 virotherapy, even if the tumor was originally resistant to the antibody." (PMID 34367166, 2021). "In one such study, tumor-harboring mice with NK-92 cells or primary NK cells transduced with retroviral vectors producing IL-2 or IL-15 had increased proliferation and persistence." (PMID 34970253, 2021). "The combination of bispecific antibodies, (Her2 x CD3) or (Her2 x Vγ2), together with the transferred Vγ2Vδ2 T cells in the presence of IL2, achieved a delay in the growth of pancreatic ductal adenocarcinoma tumor in murine models." (PMID 34040604, 2021). "There is a promising solution to prevent systemic toxicity—it requires to combine tumour-specific protein, e.g., NKG2D linked to IL-2." (PMID 33800608, 2021). "S7C) while strongly and dose-dependently attenuating rescue of IL-2 secretion and tumor killing in RestedD11-15 CAR-T cells compared to vehicle-treated control." (PMID 33795428, 2021). "Unexpected and interestingly, a recent study showed that IL-2 regulates tumor-reactive CD8+ T cell exhaustion in the middle and late tumor stages." (PMID 34639167, 2021). "Epithelial-Mesenchymal Transition (EMT), interferon gamma response, IL2/STAT5 signaling and some other pathways are activated in the high risk group, which manifest immune suppression, drug resistance, tumor evasion." (PMID 33928021, 2021).